CXCL10 (C-X-C motif chemokine ligand 10)
Diseases named in the same sentence as CXCL10 in open-access papers (continued):
Sharing a sentence is not in itself a finding about the gene and the disease.
silicosis (5 papers, 2018 to 2025). Silicosis is a respiratory disease caused by breathing in (inhaling) silica dust. "High levels of ccf-DNA in the plasma and elevated levels of C-X-C Motif Chemokine Ligand 10 (CXCL10) were found in the sputum of patients with silicosis." (PMID 40264103, 2025). "Similar findings were also observed in silica-induced silicosis patients, where increased self-dsDNA release and upregulation of CXCL10 were observed." (PMID 37965345, 2023). "Here, we show that silicosis patients with a history of intense silica exposure had increased circulating dsDNA and CXCL10 levels in sputum." (PMID 30523277, 2018). "In the lungs exposed to silica, which triggers dsDNA production, activation of the cGAS-STING signaling pathway induces lung inflammation and fibrosis, with significantly elevated levels of TNF-α, IL-6, TGF-β, and IFN-β, as well as increased levels of CXCL10 in the sputum of silicosis patients." (PMID 37965345, 2023). "In addition to viral-induced infectious pneumonia, increased dsDNA and C-X-C motif chemokine ligand 10 (CXCL10) have been detected in the sputum of silicosis patients." (PMID 37049889, 2023). "Interestingly, patients with silicosis exhibit increased circulating self-dsDNA, together with increased concentrations of CXCL10 in sputum." (PMID 30523277, 2018). "Thus, in silicosis patients, a previous intense exposure to silica leads to high self-dsDNA circulating levels and CXCL10 response." (PMID 30523277, 2018). "Importantly, silicosis patients had increased circulating dsDNA and CXCL10 in sputum, and STING was activated in lung tissue from ILD patients." (PMID 30523277, 2018).
synovitis (5 papers, 2019 to 2025). Inflammation of a synovial membrane. "Since OA is usually accompanied by synovitis, the secretion of three chemokines (CXCL6, CXCL10, and CXCL16) into the culture medium by HFLS and HFLS-OA was determined." (PMID 36233118, 2022).
urinary tract infection (5 papers, 2010 to 2023). "Urine CXCL9 and CXCL10 are also increased in patients with isolated leukocyturia and urinary tract infections and leukocyturia with increased CXCL10 demonstrates more severe inflammation than leukocyturia alone." (PMID 37675106, 2023).
uveal melanoma (5 papers, 2017 to 2025). A melanoma derived from melanocytes of the uveal tract. "Interestingly, high levels of CXCL10 correlated with survival in tebentafusp-treated patients (uveal melanoma and cutaneous melanoma)." (PMID 39204391, 2024).
viral myocarditis (5 papers, 2011 to 2025). Myocarditis that is caused by an infection with a viral agent. "An upregulation of CXCL10 expression and a decrease in viral titre were also observed in early stage viral myocarditis, indicating that CXCL10 plays a protective role in viral myocarditis." (PMID 35668739, 2021). "In viral myocarditis, Coxsackie virus B type 3 (CVB3) infection induces CXCL2 and CXCL10 expression in myocardial tissue." (PMID 35668739, 2021).
zoster (5 papers, 2012 to 2022). "Cxcl10 has been previously implicated in herpes zoster reactivation." (PMID 22815815, 2012). "CXCL10 RNA-positive cells were more abundant within two months after zoster compared to the later times." (PMID 31159224, 2019). "Induction of IP10/CXCL10 in DRG was consistent with IP10 expression in ganglion neurons of zoster patients." (PMID 26090802, 2015). "The T-cell clustering may be mediated by CXCL10 and parallels the observation in autopsied ganglia of humans after zoster." (PMID 31159224, 2019). "As observed in ganglion neurons of zoster patients, VZV infection elicits dramatic changes in the DRG xenograft cytokine milieu, including increased production of cytokines associated with neuroinflammatory responses (MCP-1/CCL2, IL-1α, RANTES and IP10/CXCL10)." (PMID 31159224, 2019). "Our demonstration of induction of CXCL10 expression in neurons after primary SVV infection is similar to earlier observations of active VZV replication, both in ganglia explants infected with VZV in vitro and in ganglia obtained at autopsy from zoster patients." (PMID 26676825, 2016).
African trypanosomiasis (4 papers, 2009 to 2025). "CXCL10 has been implicated as a key mediator in the pathogenesis of African trypanosomiasis and is considered a candidate marker for late-stage disease." (PMID 40977748, 2025). "In the brain, both neurons and glia can express Cxcl10 and astrocytes contribute to the production of CXCL10 in African trypanosomiasis." (PMID 28821016, 2017). "We demonstrated that the CSF concentration of CXCL10 is highly elevated in stage 2 patients when compared to stage 1, highlighting this molecule as a potential new staging marker for sleeping sickness." (PMID 19554086, 2009). "1.Therapeutic Targeting of CXCL10 and TNF-α: Since CXCL10 and TNF-α play significant roles in promoting neuroinflammation and disease progression, targeted therapies aimed at modulating these cytokines may improve outcomes in African trypanosomiasis." (PMID 40977748, 2025).
allergic asthma (4 papers, 2013 to 2023). A asthma with a basis in a pathological type I hypersensitivity reaction. "In our study, the positive correlation between RV RNA and CXCL10 mRNA and protein was blunted in subjects with allergic asthma." (PMID 24219422, 2013). "Interestingly, post hoc analyses suggest that allergic asthma status also affected the relationship between viral replication and induction of CXCL10, a chemokine for Th1 cells and mononuclear cells that is strongly induced by RV infection both in vitro and in vivo." (PMID 24219422, 2013).
allergic contact dermatitis (4 papers, 2019 to 2022). An inflammatory skin condition caused by an immune response to direct contact between the skin and an allergen. "CXCL10 has been previously shown to drive acute itch in a model of allergic contact dermatitis via CXCR3 signaling in sensory neurons, and is elevated in skin of AD patients." (PMID 31631836, 2019). "Allergic contact dermatitis not only elicited more itch- and pain-like behaviors than ICD in mice but also a greater upregulation in the expression of mRNA and protein for IL-1β, TNF-α, CXCL10, and CXCR3." (PMID 31875186, 2019).
Ascites (4 papers, 2016 to 2021). Accumulation of fluid in the peritoneal cavity (between the layers of the peritoneum that lines the abdomen). "Unaltered occupancy of REL and p65 at both the IL12B and CXCL10 loci in the presence of ascites strongly suggests that these gene-specific mechanisms do not affect NFκB chromatin binding." (PMID 29997615, 2018). "Gene-specific mechanisms offer a conclusive explanation why other NFκB targets such as CXCL10 are not suppressed by ascites." (PMID 29997615, 2018). "Therefore, our data do not show that mRNA synthesis of CXCL10 is prevented in the presence of ascites." (PMID 29997615, 2018). "However, in general, MX1, viperin, CXCL10, CCL8, RANTES, KC, MCP1, IL8, GM-CSF and IFNγ were readily detected in FCoV-positive cats whereby MX1 and viperin expression was higher in FCoV-positive cats with peritoneal effusions." (PMID 28388950, 2017). "Since translocation of REL and p65 is impaired in the presence of ascites, and IL12B mRNA induction is prevented, while that of CXCL10 is not, an obvious hypothesis is that these transcripts are subject to gene-specific regulation." (PMID 29997615, 2018).
avian influenza (4 papers, 2005 to 2025). Infection of domestic and wild fowl and other birds with influenza A virus. "The high elevation of CXCL10 has been reported in the plasma of patients with SARS-CoV, avian influenza H5N1, and swine-origin influenza virus -infected macrophages." (PMID 36949406, 2023).
bovine tuberculosis (4 papers, 2012 to 2025). "Thus, murine transcriptome analysis can be used to predict immunological responses in cattle allowing the prioritisation of CXCLl9, CXCL10, Granzyme A and IL-22 as potential additional readout systems for the ante-mortem diagnosis of bovine tuberculosis." (PMID 22359547, 2012).
Chagas cardiomyopathy (4 papers, 2012 to 2024). A disease of the cardiac muscle developed subsequent to the initial protozoan infection by trypanosoma cruzi. "Several studies have implicated CXCL10 in Chagas cardiomyopathy." (PMID 27795961, 2016). "Increased plasma levels of CXCL10 were detected in patients with chronic Chagas disease, and LV mRNA expression levels of CXCL10 were found to be elevated in patients with Chagas cardiomyopathy." (PMID 27795961, 2016).
chronic kidney disease (4 papers, 2020 to 2024). Impairment of the renal function secondary to chronic kidney damage persisting for three or more months. "Therefore, more studies are needed to elucidate the role of CXCL10 in chronic renal disease." (PMID 35806457, 2022).
chronic prostatitis (4 papers, 2021 to 2025). An infectious or non-infectious chronic inflammatory process that affects the prostate gland. "Our previous study showed that serum CXC10 levels were positively associated with symptoms of chronic prostatitis, and the CXCL10/CXCR3 axis could activate the p38 and ERK to induce prostate macrophage migration and cytokine release." (PMID 39718951, 2025). "Based on the association between CXCL10 and pain in chronic prostatitis, we proposed that the elevated CXCL10 may attract macrophages to the spinal cord to induce neuroinflammation and pain in chronic prostatitis." (PMID 39718951, 2025). "Because the roles of the CCL2/CCR2 axis in spinal macrophage recruitment have been elucidated, we focus on the roles of CXCL10 in neuroinflammation and pain in chronic prostatitis." (PMID 39718951, 2025). "This study demonstrated the important roles of the CXCL10/CXCR3, JAK/STAT3 and NGF/TrKA pathways in neuroinflammation and pain in chronic prostatitis, which provided novel therapeutic targets for pain management in chronic prostatitis." (PMID 39718951, 2025). "Taken together, these findings demonstrated the important roles of the CXCL10/CXCR3 axis in modulating the JAK/STAT3 pathway and inducing neuroinflammation to mediate pain in chronic prostatitis, and targeting the NGF/TrKA pathway showed therapeutic efficacy in pain treatment in chronic prostatitis." (PMID 39718951, 2025). "Because STAT3 was regulated by the JAK, we proposed that the JAK/STAT3 pathway may be downstream of the CXCL10/CXCR3 axis to induce spinal macrophage recruitment and pain in chronic prostatitis." (PMID 39718951, 2025). "CXCL10 was a ligand of CXCR3, which might bind to CXCR3 to attract macrophage infiltration in the spinal cord to induce neuroinflammation and chronic prostatitis pain symptoms." (PMID 39718951, 2025). "Hence, the JAK/STAT3 pathway in spinal macrophage may play an important role in the CXCL10/CXCR3 axis‐induced neuroinflammation and mediate pain response in chronic prostatitis." (PMID 39718951, 2025). "However, the relationship between the CXCL10/CXCR3 axis and the JAK/STAT3 pathway in neuroinflammation and pain in chronic prostatitis was unknown." (PMID 39718951, 2025).
colon adenocarcinoma (4 papers, 2018 to 2025). "In fact, a close relationship has been reported between the level of CXCL10 and the prognosis of patients with colon adenocarcinoma, clear cell renal cell carcinoma, and pancreatic adenocarcinoma." (PMID 37048082, 2023). "Irradiation increased CXCL10 production in MC38 mouse colon adenocarcinoma cells." (PMID 37048082, 2023). "Intravenous injection of MVs into mice subcutaneously transplanted with CT26 murine colon adenocarcinoma resulted in MV accumulation in the tumor tissue and enhanced production of IFN-γ as well as IP-10, also known as CXCL10." (PMID 37370364, 2023). "In addition, human colon adenocarcinomas express high levels of mRNA CXCR3 ligands and tumor endothelial cells produce CXCL9 and CXCL10 ex vivo." (PMID 29671006, 2018).
cryoglobulinemia (4 papers, 2019 to 2024). Cryoglobulinemia is a type of vasculitis that is caused by abnormal proteins (antibodies) in the blood called 'cryoglobulins.' At cold temperatures, these proteins become solid or gel-like, which can block blood vessels and cause a variety of health problems. "For instance, CXCL10 levels were much higher in patients with HCV-associated cryoglobulinemia compared with those patients with autoimmune thyroiditis." (PMID 36366543, 2022). "Additionally, high CXCL10 levels present in cases of HCV-associated cryoglobulinemia were associated with the presence of another extrahepatic manifestation, i.e., active vasculitis." (PMID 36366543, 2022). "Moreover, increased values of CXCL10 and TNF-alpha were measured in individuals with HCV-associated cryoglobulinemia." (PMID 31244756, 2019).
diabetic neuropathy (4 papers, 2020 to 2025). A chronic, pathological complication associated with diabetes mellitus, where nerve damages are incurred due to diabetic microvascular injury involving small blood vessels that supply these nerves, resulting in peripheral and/or autonomic nerve dysfunction. "On the contrary, several negative correlations were found between suralis nerve conduction data and CXCL10 levels, indicating that Th1‐mediated inflammation may be associated with diabetic neuropathy severity." (PMID 37021432, 2023). "Elevated levels of CRP, interleukin (IL)-1, IL-6, C-X-C motif chemokine ligand 10 (CXCL10), tumor necrosis factor (TNF)-α, IL-12 (p70), IL-13, and IL-17A are associated with an increased risk of T2DM and diabetic neuropathy." (PMID 39408723, 2024). "Moreover, CCL-2/MCP-1 and CXCL-10/IP-10 levels were higher in patients with diabetic neuropathy over those with leprosy neuropathy." (PMID 32038662, 2020).
Ebola (4 papers, 2016 to 2019). "For example, by 4 days post-infection the expression level of CXCL10 had gone up 7.1-fold in the Ebola-naïve group, but only 3.1-fold in the vaccinated group." (PMID 27595844, 2016).
gingivitis (4 papers, 2019 to 2025). A disorder involving inflammation of the gums; may affect surrounding and supporting structures of the teeth. "Furthermore, we found that gingivitis biofilm in particular could activate CCL5 (MyD88-dependent and independent) transcription and cariogenic biofilm could activate CXCL10 (MyD88-independent) transcription." (PMID 31448244, 2019).
Guillain-Barre syndrome (4 papers, 2018 to 2022). A spectrum of rare post-infectious neuropathies that usually occur in otherwise healthy patients. "CXCL10 has also been strongly implicated in Guillain-Barré syndrome pathogenesis." (PMID 29768624, 2018). "In this study IP-10 (CXCL10), has shown to be involved in ZIKV-related fetal neuron apoptosis or Guillain-Barré syndrome, and is suggested as potential biomarker of acute infection." (PMID 30359380, 2018). "Thus, we hypothesize that the high levels of CXCL10 in ZIKV patients may contribute to neuronal damage affecting the developing foetal brain and potentially targeting peripheral nerves in Guillain-Barré syndrome as well." (PMID 29768624, 2018).
helminth infection (4 papers, 2016 to 2024). "During helminth infection and in response to increased levels of IFNγ, EGCs upregulate C-X-C motif chemokine ligand 10 (CXCL10) to recruit IFNγ+CD8+ T cells to the tunica muscularis in order to amplify the IFNγ tissue response and propagate immune cell activation." (PMID 35533467, 2022). "It would be particularly interesting to identify what cues drive these pathways during helminth infection, and whether the previously identified regulator of epithelial turnover, CXCL10, plays any role." (PMID 27598373, 2016).
HIV encephalitis (4 papers, 2010 to 2020). "The chemokines CXCL10 and CXCL11 were assessed because we found their levels to be elevated in the brain of HIVgp120tg mice and CXCL10 has been linked to neuronal dysfunction and found to be overexpressed in the CNS of HIV encephalitis (HIVE) patients." (PMID 32727588, 2020). "Increased expression of CXCL10 and CXCL8 in astrocytes was also reported in brains of individuals with HIV encephalitis." (PMID 20877724, 2010).
interstitial cystitis (4 papers, 2015 to 2022). A rare chronic debilitating urogenital disease characterized by urinary frequency, urgency, and pelvic pain. "Blockade of receptors activated by CXCL10 has been shown to increase bladder capacity, reduce bladder contractility and nerve sensitivity in a murine model of interstitial cystitis." (PMID 33657181, 2021). "Clinical relevance of CXCL-10 in bladder function and urinary symptoms can be gleaned from the upregulated gene expression of CXCL-10 in bladder biopsy of ulcerative cystitis patients." (PMID 25991911, 2015).
intracerebral haemorrhage (4 papers, 2023 to 2025). "Interestingly, patients with higher blood levels of CXCL10 have been associated with a worse prognosis following intracerebral haemorrhage." (PMID 38861234, 2025). "Elevated CXCL10 levels have been found in the cerebrospinal fluid of patients with neonatal post-hemorrhagic hydrocephalus and in serum of neonatal and adult patients with perinatal asphyxia and intracerebral hemorrhage respectively." (PMID 38715091, 2024).
leptospirosis (4 papers, 2014 to 2022). A contagious bacterial infection caused by spirochetes of the genus Leptospira. "Pro-inflammatory cytokines and enzymes which were IL-1β, IL-6, TNF-ɑ, IFN-γ and COX-2 and chemokines CXCL10/IP-10 and CCL3/MIP-α showed upregulation as reported in both human and animal leptospirosis." (PMID 35584087, 2022). "High levels of IL-1β, CXCL10/IP-10, CCL3/MIP-α, neutrophils and low levels of lymphocytes and platelets might serve as a cumulative panel of biomarkers in severe leptospirosis." (PMID 35584087, 2022). "This study deciphered haemorrhage as the earliest manifestation of severe leptospirosis and high levels of IL-1β, CXCL10/IP-10, CCL3/MIP-α, neutrophils and low levels of lymphocytes and platelets serve as a cumulative panel of biomarkers in severe leptospirosis." (PMID 35584087, 2022). "Both MIP-1α/CCL3 and IP-10/CXCL10 chemokines are important chemotaxis potents on leucocytes and murine models of the disease showed infiltration of CD11b+ macrophages and CD3+ lymphocytes in renal tissues during chronic leptospirosis." (PMID 27219334, 2016). "The increased expression of IL-1β, CXCL10/IP-10, CCL3/MIP-α, high neutrophils and low lymphocytes and platelets production observed in the present study indicate that these parameters could serve as a cumulative panel of biomarkers in severe leptospirosis." (PMID 35584087, 2022). "The early expression of IL-1β, CXCL10/IP-10 and CCL3/MIP-α, increase of neutrophils and decrease of lymphocytes and platelets suggesting that these parameters could be used as a cumulative panel for potential biomarkers in severe leptospirosis." (PMID 35584087, 2022). "Taken all these data together, we suggest that high levels of IL-1β, CXCL10/IP-10, CCL3/MIP-α, neutrophils and low levels of lymphocytes and platelets could serve as a cumulative panel of potential biomarkers in the disease progression from mild to severe in leptospirosis." (PMID 35584087, 2022).
leukocytosis (4 papers, 2017 to 2023). "HGF, IL-6, IL-8, and IP-10/CXCL-10 are associated with the presence of JAK2V617F mutation and a proliferative phenotype (leukocytosis and hepatosplenomegaly)." (PMID 37760903, 2023).